AR (androgen receptor)
Diseases named in the same sentence as AR in open-access papers (continued):
Sharing a sentence is not in itself a finding about the gene and the disease.
prostate carcinoma (continued). "We suggest that SNCG is a novel co-activator of AR and may play an important role in the molecular interaction with AR signaling in prostate cancer cells." (PMID 23231703, 2012). "The androgen receptor (AR) is a critical regulator of prostate cancer progression and it is increasingly clear that the AR is regulated not only by its cognate steroid hormone, but also by interactions with a constellation of co-regulatory and signaling molecules." (PMID 22761715, 2012). "In addition, the stabilization of androgen receptor protein in prostate cancer cells changes with the transition of androgen requirement." (PMID 23304206, 2012). "AR is a key protein functioning as a nuclear transcription factor in prostate cancer cells that may be used on a panel for prostate cancer screening." (PMID 22641253, 2012). "We hypothesized that in androgen dependent prostate cancer cells antagonist bound AR binds a unique set of target genes, that might differ from the target genes of agonist bound AR." (PMID 23056316, 2012). "The androgen receptor (AR) is postulated to play a key mediator of prostate cancer." (PMID 22754355, 2012). "In addition to ligand specificity, NcoA4 overexpression reverses the antagonistic activity of hydroxyflutamide, an AR antagonist widely used in the treatment of prostate cancer." (PMID 22562579, 2012). "As JQ1 has such a dramatic effect on AR-regulated transcription, and LNCaP cell proliferation, these findings further raise the potential of therapeutic use of this compound in the treatment of prostate cancer." (PMID 23144632, 2012). "One of the findings we were able to retrieve using the integrative approach is the nuclear receptor coactivator NCOA2 that was previously shown to alter AR pathway in primary prostate tumors providing mechanism for its potential role as a prostate cancer oncogene." (PMID 22811706, 2012). "To examine whether AR protein physiologically interacts with SNCG protein in human prostate cancer cells, we performed a co-immunoprecipitation assay." (PMID 23231703, 2012). "Androgen receptor mediated signaling drives prostate cancer cell growth and survival." (PMID 22403669, 2012). "AR also performs a crucial function in prostate cancer cell proliferation, and thus the levels of COUP-TF II expression may affect prostate cancer growth." (PMID 23145053, 2012). "Further, it has been suggested that one function of AR in PTEN-deficient prostate cancer cells is to promote the pathologic activation of mTOR, providing a potential mechanistic link between these two pathways in prostate cancer." (PMID 22614157, 2012). "To determine the relationship between AR-dependent chromatin accessibility changes and AR-mediated transcription, we performed DNase-seq and mRNA-seq on the well-established androgen-sensitive prostate cancer cell line LNCaP, before and after hormone induction." (PMID 23034120, 2012). "The AR is a transcription factor and a primary driver of prostate cancer." (PMID 23034120, 2012). "Androgen receptor (AR) is involved in the development and progression of prostate cancers." (PMID 23145053, 2012). "In addition, the ability of AR to crosstalk with other key growth factor signaling pathways in prostate cancer has been established." (PMID 22614157, 2012). "This study extends the pool of recognized putative AR targets and identifies a negatively regulated target of AR – COUP-TF1 – which could possibly play a role in human prostate cancer." (PMID 23056316, 2012). "Targeting AR through androgen ablation therapy is the mainstay of prostate cancer treatment." (PMID 22614157, 2012).
prostate carcinoma (continued). "Recent data suggests that AMPK activation may have more complex regulation in prostate cancer cells and may potentiate increased prostate cancer cell proliferation and migration when activated downstream of the androgen receptor (AR)." (PMID 22548055, 2012). "Using microarray studies, we show that resveratrol reduced the expression of various prostate-tumor associated microRNAs (miRs) including miR-21 in androgen-receptor negative and highly aggressive human prostate cancer cells, PC-3M-MM2." (PMID 23272133, 2012). "Moreover, an oncogenic role of GASC1 has been documented in prostate cancer where it enhances the transcription of androgen receptor-dependent genes and cell proliferation by interaction with ligand-bound androgen receptor." (PMID 23148692, 2012). "p38 seems to play a critical role in hypoxia-reoxygenation-induced increase in AR activity, as well as increased survival, clonogenicity, and invasiveness in prostate cancer cells, thus providing additional support for a role for p38 in androgen dependence acquisition." (PMID 22046506, 2012). "Further studies are needed to elucidate the complex interplay between sex hormones and KCNMA1 in breast- and prostate cancer that is likely to be influenced by the type of regulatory ß-subunits of the BK channel, alternative splicing, the background of ER and/or AR status, and anti-hormone therapy." (PMID 22899999, 2012). "In addition to prevailing alterations in AR expression and function, approximately half of prostate cancer samples harbor an oncogenic gene fusion combining androgen-regulated transmembrane protease serine 2 (TMPRSS2) with oncogenic ETS transcription factors." (PMID 22761906, 2012). "Dual inhibition of the AR and mTOR signaling pathways provided further benefit with the ridaforolimus-bicalutamide combination producing synergistic antiproliferative effects in prostate cancer cells in vitro when compared with each agent alone." (PMID 22614157, 2012). "It will be worthwhile to investigate whether cell arrest function of COUP-TF II is also observed in prostate cancer cells and whether the function is related with its inhibitory function of AR transactivation." (PMID 23145053, 2012). "EGFR may also sensitize prostate cancer cells to low levels of androgens by enhancing co-activator binding and transcriptional activation of endogenous and ectopically expressed AR." (PMID 23185449, 2012). "Besides regulating the development and maintenance of the prostate, androgens support the development and growth of most primary prostate cancers, and androgen receptor (AR) plays the role of an oncogene in prostate cancer." (PMID 22761906, 2012). "Herein, we describe an in vitro model for assessing the effects of continuous androgen-deprivation on prostate cancer cells (LNCaP) with respect to the expression of two prostate-specific markers: the androgen receptor (AR) and prostate-specific membrane antigen (PSMA)." (PMID 23041906, 2012). "Throughout prostate cancer progression including HRPC, AR overexpresses or undergoes mutations." (PMID 22666381, 2012). "Androgen deprivation therapy remains the most powerful treatment for advance prostate cancer and newer generation androgen deprivation therapies (ADTs) that more effectively inhibit AR signaling are rapidly being developed and approved for patients with metastatic CRPC." (PMID 22454635, 2012). "The androgen receptor (AR) is known to play a critical role in prostate cancer (PC)." (PMID 22383394, 2012). "Additionally, small molecule inhibitors of histone deacetylases have been shown to decrease the growth rate of AR-positive prostate cancer cell lines and disrupt AR-induced expression of its target genes." (PMID 23034120, 2012). "Moreover, inhibition of EGFR/HER2 signaling can inhibit prostate cancer cell growth in vitro and in vivo as well as AR transcriptional activity, protein stability, DNA binding, and Ser 81 phosphorylation." (PMID 22761715, 2012).
prostate carcinoma (continued). "To determine the impact and specificity of AR antagonist treatment on prostate cancer growth, we first assessed the effect of Compound 26 and 30 on cell viability using various pre-clinical models, including AR-positive VCaP cells and AR-negative DU145 and PC3 cells." (PMID 22849360, 2012). "The androgen receptor (AR) is a critical factor for prostate cancer development and progression." (PMID 23056607, 2012). "Prostate cancer growth and progression depend on androgen-induced AR signaling." (PMID 23019221, 2012). "Therefore, the widely held opinion that AR mutations in androgen insensitivity syndrome (AIS) and in prostate cancer result in loss and gain of function respectively is at best an over simplification." (PMID 22403669, 2012). "Therefore, in the current study, we investigated the effects of B-DIM on AMPK signaling and its related downstream targets in both androgen-sensitive LNCaP and androgen-insensitive C4-2B prostate cancer cells containing functional AR." (PMID 23056607, 2012). "However, during prostate carcinogenesis, the regulatory function played by the androgen receptor is often converted from a growth suppressor to an oncogene which in turn stimulates prostate cancer cell survival and proliferation." (PMID 21378414, 2011). "This hypothesis is supported by numerous reports that the AR itself is expressed in the majority of prostate cancers and often amplified in metastasis and therapy-resistant tumors." (PMID 21829708, 2011). "The mechanisms for this selective modulation of the AR pathway during prostate cancer progression are yet undefined, but we speculate that it may be dictated by an imbalance in AR co-regulators and/or interactions with other signaling pathways." (PMID 21829708, 2011). "An AR gene harboring a gain-of-function mutation which is constitutively active can thus render prostate cancer cells independent of androgen and with a castration-resistant phenotype." (PMID 24212771, 2011). "However, there is evidence from in vitro experiments that in castration-resistant prostate cancer (CRPC) cells the AR is able to translocate into the nucleus in a ligand-independent manner." (PMID 21980429, 2011). "Furthermore, Wnt3a treatment increased the self-renewal of putative PCSCs independent of androgen signaling, and Wnt11 expression was shown to be inversely correlated to AR expression in prostate cancer cell lines and primary cultures." (PMID 24212796, 2011). "Furthermore, our data show that Pax6 and AR are coexpressed in the androgen insensitive prostate cancer cell line PC3, the lens epithelial cell line B3, in addition to the cancer cell lines HEK293 and HeLa." (PMID 21935435, 2011). "Since specific antibodies detecting all C-terminal truncated AR variants are not available, our aim was to develop an approach to assess the prevalence and function of AR variants in prostate cancer (PCa)." (PMID 22114732, 2011). "Therefore, both AR+ and AR- cells were capable of forming androgen-independent prostate cancer cells as the tumorigenesis progresses to the more advanced stages." (PMID 21241512, 2011). "Indeed, alterations in several AR co-activators and co-repressors have been previously detected in prostate cancer and, in particular, in hormonal therapy-resistant disease." (PMID 21829708, 2011). "We speculate that androgen dependence and/or the androgen receptor expression status of prostate cancer cells may influence RSV-mediated modulation of the innate antiviral apparatus (NF-κB activation vs. IFN-mediated JAK/STAT activation)." (PMID 21276246, 2011). "The recent finding that inhibition of the glycogen-synthase-kinase 3β (GSK-3β) induces a rapid nuclear export of the AR in androgen-stimulated prostate cancer cells prompted us to analyze the effects of a GSK-3β inhibition in the castration-resistant LNCaP sublines C4-2 and LNCaP-SSR." (PMID 21980429, 2011). "The AR is a critical effector of prostate cancer development and progression." (PMID 22191037, 2011).
prostate carcinoma (continued). "Therefore, AR signaling has long been recognized as a main target for prostate cancer prevention and treatment." (PMID 22200028, 2011). "In the present study, we focused on the role of the AR pathway in prostate cancer progression." (PMID 21829708, 2011). "Also, androgen receptor expression in prostate cancer has long been known to be regulated, in part, by methylation." (PMID 21789170, 2011). "Therefore, under androgen-depleted conditions, ADI prostate cancer cells appear to develop intracellular strategies that activate the AR signaling pathway." (PMID 21267413, 2011). "In view of the persistence of both AR and tissue androgens in recurrent prostate cancer, therapies that directly target the AR, or affect the persistence of androgens in prostate tissue, may be of value for patients with CRPC." (PMID 21513551, 2011). "Cell culture and xenograft studies using androgen receptor (AR)-positive castration-resistant human prostate cancers cells (LNCaP, ARCaP, and PC-3 cells over-expressing AR) suggest that androgens may suppress the growth of AR-rich prostate cancer cells." (PMID 21859492, 2011). "However in the course of prostate cancer development, there is a phase when castrated levels of testosterone fail to inhibit the growth of malignant cells, even if they still require androgen receptor activity for their growth." (PMID 22191056, 2011). "These prostate cancer-specific gene rearrangements may be explained by the fact that androgen treatment in AR-positive prostate cancer cell lines induced proximity between TMPRSS2 and ERG." (PMID 22110995, 2011). "AR is another important target for hormonal therapy in for example prostate cancer." (PMID 22613849, 2011). "Several other mechanisms also may result in activation of the AR in prostate cancer in the face of castrate levels of androgen." (PMID 21513551, 2011). "This may explain the abundant AR- cancer cells found in many high grade prostate cancers and the failure of androgen deprivation therapies." (PMID 21241512, 2011). "Recent studies revealed that although androgen deprivation therapy significantly reduced serum testosterone concentrations, levels of testosterone and dihydrotestosterone occur in recurrent prostate cancer tissue are sufficient to stimulate AR transcription, PSA secretion, and tumor growth." (PMID 21859492, 2011). "Since several clinical trials already confirmed that testosterone is a safe, feasible, and reasonably well-tolerated therapy for men with early hormone-refractory prostate cancer, we believe that manipulating androgen/AR signaling can be a potential therapy for AR-positive advanced prostate cancer." (PMID 21859492, 2011). "However, the results of our present study showed a selective down-regulation of AR target genes, questioning the over-simplistic view of the AR pathway as the driving force for prostate cancer growth and proliferation." (PMID 21829708, 2011). "This points to the fact that we may need combination therapy, possibly inhibiting 5α-reductase isoenzymes, the AR, and other factors involved in ligand-independent AR activation for efficient prevention of prostate cancer in all men." (PMID 22194926, 2011). "The delay of progression toward androgen-independency in IAD treatment might be related to the suppressive effect of androgen on AR-positive hormone-refractory prostate cancer cells that is observed in the LNCaP and other prostate cancer cell models." (PMID 21859492, 2011). "In addition, Sam68 is considered an AR co-activator as it can modulate AR transcriptional activity in prostate cancers." (PMID 22073224, 2011).
prostate carcinoma (continued). "On the other hand, the activation of other signal transduction pathways, such as BCL-2 activation, may also bypass the requisite of AR activation for the proliferation and survival of prostate cancer cells." (PMID 21267413, 2011). "We have shown that INPP4B is directly regulated by AR in LNCaP and VCaP prostate cancer cells." (PMID 21487159, 2011). "Manipulating androgen/AR signaling may therefore be a potential therapy for AR-positive advanced prostate cancer." (PMID 21859492, 2011). "Recently, multiple kinds of AR alternative splicing variants lacking various portions of the ligand-binding domain (LBD) were identified in human prostate cancer specimens." (PMID 22110995, 2011). "The androgen receptor (AR) regulates benign prostate and prostate cancer growth." (PMID 24213129, 2011). "Additionally, as a co-activator of Androgen receptor (AR), Tip60 contributes to the progression of chemotherapeutic-resistant prostate cancer cell proliferation." (PMID 21781306, 2011). "AR is essential for all phases of prostate cancer progression including the terminal CRPC stage." (PMID 21909421, 2011). "Due to the central role of AR in all phases of prostate cancer, modulating AR protein stability or AR cofactor activity represents an effective strategy to overcome most of the mechanisms of resistance and may have therapeutic implications in this disease." (PMID 22111003, 2011). "A promotional role of AR co-regulators in prostate cancer progression has also been suggested." (PMID 21949845, 2011). "Transduction by an antibiotic-selectable AR-expression lentivirus allowed us then to derive a stable cell line, WPMY-AR, that expressed AR mRNA and protein at a level comparable to LNCaP cells that are often used to model a prostate cancer cells' response to androgens." (PMID 21267466, 2011). "The abrogation of TPL2-mediated PSA promoter activation in AR-negative DU-145 prostate cancer cells suggests that TPL2-mediated ADI prostate cancer growth may be still dependent on AR activity." (PMID 21267413, 2011). "Moreover, recent studies haveestablished a link between HH/GLI and AR signalling in the androgen-dependent (AD),luminal epithelial LNCaP prostate cancer cell line and demonstrated that GLI1maintains cell viability in the absence of AR activity." (PMID 21633508, 2011). "AR plays an important role in both early and advanced stages of prostate cancer etiology." (PMID 21935435, 2011). "It has been reported that Sam68, as an alternative splicing regulator and interacting protein of RBMY, might modulate AR-regulated transcriptional activity in prostate cancer cells." (PMID 22073224, 2011). "By far the most studied transcriptional activator in prostate cancer is the androgen receptor (AR)." (PMID 22191037, 2011). "Further studies into the molecular mechanisms by which ZMIZ1 regulates AR mediated transcription may provide new insight into the biological role of ZMIZ1 in prostate cancer and related human disorders." (PMID 21949845, 2011). "Similarly, the expression of AR in LNCaP prostate cancer cells exposed to MF decreased, a slight decrease in the abundance of ER-α was observed in MCF-7 and SK-OV-3 cells, whereas GR-α slightly declined in some but not all cell lines treated with MF." (PMID 21619605, 2011). "Treatment of the PC-3/AR prostate cancer cell line, which overexpresses AR, with dihydrotestosterone (DHT) induced endogenous ZEB1 mRNA and protein, confirming our observations that androgen increases ZEB1 mRNA and showing for the first time that this is reflected in ZEB1 protein levels." (PMID 22190929, 2011). "Androgen receptor (AR) is required for the survival and growth of prostate cancer cells." (PMID 21909421, 2011). "The fact that Wnt signaling may augment AR signaling has implications for therapy due to the frequent recurrence of prostate cancer after androgen deprivation therapy." (PMID 24212796, 2011).